MTOR (mechanistic target of rapamycin kinase)
Diseases named in the same sentence as MTOR in open-access papers (continued):
Sharing a sentence is not in itself a finding about the gene and the disease.
leukemia (continued). "In a mouse model, Grp78 knock‐out suppressed the activation of the AKT/mTOR pathway and the accumulation of leukemic blasts, suggesting that Grp78 may play an important role in leukemia progression." (PMID 35846080, 2021). "Because IL7R mutant leukemias exhibited clear upregulation of mTOR signaling, we administered the clinical-grade dual PI3K and mTOR inhibitor dactolisib and found it had a striking impact on the frequency of leukemia cells in the blood, significantly prolonging the survival of transplanted mice." (PMID 34907175, 2021). "Uptake of the dipeptide Gly-Sar can mediate mTOR activity in leukemia stem cells." (PMID 35003157, 2021). "Furthermore, despite its role in leukemia cells, mTOR activity is crucial for hematopoietic stem cell (HSC) proliferation and self-renewal potential." (PMID 33742137, 2021). "Moreover, it is demonstrated that other pathways like mTOR-related cytotoxic autophagy can be induced by idarubicin in leukemia cancerous cells." (PMID 33936221, 2021). "Inhibitors of the mTOR-pathway are currently one line of therapies for leukemia patients." (PMID 33802234, 2021). "Full transformation associates with transcriptional upregulation of oncogenes such as Myc or Bcl2, downregulation of tumor suppressors such as Ikzf1 or Arid2, and major IL-7R signaling upregulation (involving JAK/STAT5 and PI3K/mTOR), required for leukemia cell viability." (PMID 34907175, 2021). "mTOR was downregulated in RNF126-overexpressing leukemia cells." (PMID 32131492, 2020). "It represents a novel epigenetic mechanism of AKT/mTOR activation in leukemia." (PMID 32962037, 2020). "In addition, an AMPK/mTOR-dependent mechanism has been involved in the induction of apoptosis in leukemia cells by suppressing c-myc expression." (PMID 33072590, 2020). "The present study examined whether NTS could be used as a novel therapeutic agent for leukemia and whether mTOR ubiquitination and degradation pathways could function as the antileukemic mechanism of NTS." (PMID 32131492, 2020). "Metformin inhibits AKT/mTOR signaling, and might therefore be an effective approach to treat leukemia." (PMID 32425881, 2020). "ROS inhibition prevented RNF126 expression and mTOR ubiquitination in NTS-treated leukemia cells." (PMID 32131492, 2020). "In addition, our study offers strong evidence that RNF126 is a novel tumor-suppressive E3 ligase that regulates mTOR in leukemia cells." (PMID 32131492, 2020). "In T-ALL, a vital role in Notch-driven thymocyte differentiation and leukemia has been assigned to mTOR complex 2, suggesting a potential role of mTOR C2 inhibition in undifferentiated T-ALL; however, activation of the PI3K axis is a common feature among T-ALL independent of differentiation stage." (PMID 32993794, 2020). "For example, HMGB1 induces drug resistance by activating leukemia cell autophagy via the PI3K/Akt/mTORC1 pathway, and reduced expression of HMGB1 activates mTOR and promotes the phosphorylation of Akt and p70S6k, inhibiting leukemia cell autophagy and increasing drug sensitivity." (PMID 30157958, 2018). "Gene expression profiling revealed differential upregulation of MAPK, PI3-K/mTOR, WNT, and JAK/STAT pathway genes in BPL cells from CD22ΔE12-Tg mice closely mimicking the transcriptome of primary leukemia cells from high-risk BPL patients (Accession #GSE58872 and GSE58874)." (PMID 31788667, 2018). "The advances in the comprehension of the biological impact that mTOR has in the leukemia setting, described in this review, could contribute to the potential future development of effective mTOR-targeting based therapeutics." (PMID 30110936, 2018). "Based on the in vitro and ex vivo data, we hypothesized that the combinations of a type II JAK2 inhibitor and an mTOR inhibitor would achieve better anti-leukemia control in the in vivo Ph-like B-ALL PDX models." (PMID 29487712, 2018).
leukemia (continued). "We next tested whether mTOR inhibition can interfere with leukemia initiation when combined with pharmacological autophagy inhibition." (PMID 29165716, 2018). "Targeting mTOR has been proved to be effective for leukaemia therapy." (PMID 28026112, 2017). "Thus, mTOR inhibitors were investigated in preclinical and clinical antitumor studies, such as leukemia, lymphoma, endometrial carcinoma, renal carcinoma, breast cancer and glioblastoma." (PMID 28186963, 2017). "Recent research demonstrated that various NPs modulate the activation of mTOR and even may result into cell cycle arrest in leukemia cells." (PMID 29167516, 2017). "AKT inhibitor MK2206 synergistically enhanced prednisolone sensitivity in leukemia cells from 8/11 patients, while mTOR inhibitors AZD8055 and everolimus acted synergistically when combined with prednisolone in 10/11 and 8/8 patient samples, respectively, including both steroid-resistant patients." (PMID 27997540, 2016). "Thus, PI3K-Akt-mTOR targeting will not only affect leukemic cells but also their neighbouring leukaemia-supporting stromal cells." (PMID 27845732, 2016). "Our data suggest that Rheb1 promotes AML progression through mTORC1 signaling pathway and combinational drug treatments targeting Rheb1 and mTOR might have a better therapeutic effect on leukemia." (PMID 27071307, 2016). "Attempts have been recently made to apply mTOR inhibitors in treatment of leukemia, including CLL." (PMID 27147570, 2016). "Alterations of PI3K/AKT/mTOR are predominant in T-ALL with respect to other leukemia types." (PMID 26056603, 2015). "Re-investigating our gene expression data set employing gene set enrichment analysis, we identified enrichment of the TTL profile in mTOR-annotated gene sets further supporting that mTOR signaling is involved in driving rapid leukemia engraftment and early patient relapse." (PMID 25682198, 2015). "Minimal remodeling regions are associated with gene ontologies specific to decreased B cell number and mTOR inhibition and may make unique contributions to glucocorticoid-induced leukemia cell death." (PMID 26633995, 2015). "Taken together, rapamycin inhibits highly activated mTOR signaling in TTLshort/high-risk ALL resulting in blocked proliferation of leukemia cells upon ex vivo exposure and, most importantly, after in vivo treatment of mice with manifest leukemia." (PMID 25682198, 2015). "In myeloid cells mTOR, a highly conserved serine/threonine kinase, acts as a central regulator of cell growth and metabolism and plays crucial pathophysiological roles in host immune defence, allergic reactions and leukaemia." (PMID 26384306, 2015). "mTOR inhibitors have been found to have additive or synergistic effects when combined with cytotoxic chemotherapy agents, as well as to reverse chemotherapeutic resistance in some leukemias." (PMID 24904824, 2014). "Numerous strategies have been used to target aberrant PI3K/mTOR pathway signaling in leukemias." (PMID 24904824, 2014). "Indeed, for example, rapamycin, an mTOR-specific inhibitor, prevents leukemia development in PTEN-null mouse models." (PMID 25426449, 2014). "To address whether the effects on the target proteins were specific to CML or apparent in other mTOR-dependent leukaemias, we tested the Jurkat leukaemia T-cell line." (PMID 25392452, 2014). "BCR-ABL directly activates the PI3K/mTOR pathway, which may explain some of the robust preclinical activity of MTIs in these leukemias." (PMID 24904824, 2014). "Moreover, Pten/mTOR and the PI3K/Akt signalling pathway have been shown to be implicated in AML development and leukemia stem cell population maintenance." (PMID 24952669, 2014). "Initial studies using (non-CRLF2-rearranged) murine B-ALL models identified activation of PI3K/mTOR signaling in these leukemias, which was modulated by IL-7 and TSLP and could be abrogated in vitro and in vivo by sirolimus treatment." (PMID 24904824, 2014).
leukemia (continued). "Our study shows that the DEK-NUP214 fusion gene increases proliferation by upregulation of mTOR, suggesting that patients with leukemias carrying DEK-NUP214 may benefit from treatment with mTOR inhibitors." (PMID 24073922, 2013). "Interestingly, our findings indicated that one of the most affected signaling pathways in U937 leukemia cells was the phosphatidylinositol 3-kinase (PI3K)-Akt-mammalian target of rapamycin (mTOR) cascade." (PMID 23861714, 2013). "The sensitivity of leukemia cells to combinations of glycolytic inhibitors, such as 2-DG and 3-BrPA, and inhibitors of oxidative phosphorylation (antimycin A) or the mTOR pathway (rapamycin analogues) suggests a potential role for combinatorial therapeutic approaches in HMs." (PMID 24024216, 2013). "This demonstrates that the proliferative effect is dependent on mTOR and suggests that cells carrying the DEK-NUP214 fusion gene may be sensitive to treatment with the mTOR inhibitors currently being evaluated for the treatment of leukemia." (PMID 24073922, 2013). "Previous studies reported that RHEBL1 could function as an activator of NF-kB and mTOR signaling, both of which are frequently altered in many solid tumors, as well as in leukemias and lymphomas." (PMID 24127550, 2013). "Dual inhibitors (inhibiting both mTORC1 and mTORC2 complexes) may be a solution for mTOR inhibition in rapamycin resistant cases, and promising experimental results have been published about their effect in leukemia cells." (PMID 23573198, 2013). "mTOR inhibitors have gained attention for their efficacy in combating Ph+ leukemias." (PMID 22693568, 2012). "Given that the PTEN/AKT/mTOR pathway plays an essential role in leukemia-initiating cells, the evaluation of this pathway in a purified leukemia population may provide some important insights." (PMID 21795762, 2011). "Targeting mTOR signaling pathway can be a new strategy for the treatment of leukemia." (PMID 19115995, 2008). "Importantly, the observation that Hsp90 and mTOR are involved in human telomerase activity in primary cells from patients with NK cell lymphoma or leukemia corroborates the upregulation of the Akt/Hsp90/mTOR/S6K signaling pathway in telomerase activity observed in these patients." (PMID 40249925, 2025). "Finally, we directly tested whether taurine could promote mTOR interactions with lysosomes in wild-type and Slc6a6−/− leukaemia cells expressing RAGA(Q66L)." (PMID 40369079, 2025). "In addition, LAPTM4B stimulated the mTOR pathway in EVI1hi leukemia cells." (PMID 39680456, 2024). "In this review, we outline the role of the PI3K/Akt/mTOR signaling pathway in blood malignancies’ cells and gather information on the inhibitors of this pathway that might provide a novel therapeutic opportunity against leukemia." (PMID 37958470, 2023). "Further, rapamycin‐treated leukemia cells were presented with smaller cell and nuclear sizes, pharmacologically reversing the effect of Kmt2d knockdown, further providing experimental evidence for the role of the mTOR signaling pathway played in the tumorigenesis." (PMID 37142882, 2023). "Similarly, others have shown that mTOR inhibition is chemoprotective in leukemia cells." (PMID 36396656, 2022). "Furthermore, We performed a chemical screening, suggesting that USP30 inhibitors may synergize with AKT/mTOR inhibitors in treating leukemia." (PMID 35250566, 2022). "In hematopoietic cells, the PI3K/AKT/mTOR pathway is an important regulator of cell growth, proliferation, and survival; the amplification and deregulation of this pathway confer resistance to apoptosis, growth inhibition, and differentiation on leukemia cells." (PMID 33401428, 2021). "The assumption that mTOR activation is leading to the exhaustion of NK cells in leukemic mice led us to hypothesize that targeting mTOR pathway would at least reduce some of the observed effects of leukemia progression." (PMID 34975835, 2021).
leukemia (continued). "However, RNF126 was found to induce the downregulation of mTOR in leukemia cells." (PMID 32131492, 2020). "Therefore, the inhibition of the PI3K/AKT/mTOR pathway may assist in eradicating leukaemia blasts, and there is ongoing work aimed at developing an inhibitor that will be useful in the clinic (as reviewed in Ref." (PMID 28819864, 2018). "We could show that PS-NH2 inhibits, whereas PS-COOH activates the mTOR signaling in leukemia cells." (PMID 25671136, 2014). "Moreover, in light of the possible use of mTOR inhibitors as adjuvant therapy in leukemia, our data suggest that their efficiency in combination with cytarabine might be further improved by inhibition of the concomitant autophagic response." (PMID 24714637, 2014). "Moreover, in our studies, normal mononuclear cells were significantly less inhibited by dual PI3K/MTOR inhibition than leukemia cells, indicating a therapeutic gap of these agents in the treatment of acute leukemia without significant suppression of normal hematopoiesis." (PMID 23705826, 2013). "Therefore, the observations of the opposing effects of rapamycin on normal hematopoietic and leukemia stem cells or the preferential sensitivity of CSCs to mTOR inhibition compared with normal cells cannot be explained only by the shared function of the stemness pathways." (PMID 24231729, 2013). "Additional studies demonstrated that TSLP stimulation of CRLF2-rearranged leukemia cells resulted in aberrant STAT5 and PI3K/mTOR pathway signaling." (PMID 40787610, 2025). "Our data agree with previously reported gnetin C activity on AKT/mTOR signaling in leukemia cells, in which gnetin C’s antitumor effects are demonstrated in cancer cell lines, patient samples, and in vivo through AKT/mTOR and ERK1/2 pathways." (PMID 38611022, 2024). "Various small molecule inhibitors, including those targeting protein kinases, epigenetic modifiers, PI3K/Akt/mTOR signaling, and apoptosis regulators, have demonstrated potential synergistic effects when combined with CAR-T therapy for leukemia." (PMID 39329777, 2024). "In the MOLT-4 human leukemia cell line, quercetin interacts with the PI3K-dependent/AKT pathway, leading to a decrease in mammalian target of rapamycin (mTOR) activity." (PMID 38169656, 2024). "We evaluated the mechanism of action of hesperetin on human leukemia cells, focusing on autophagy, particularly the AMPK/Akt/mTOR pathway." (PMID 36826047, 2023). "Leukemia blast suppression following PRL2 inhibition was correlated with an increase in PTEN and downregulation of AKT/mTOR-regulated pathways." (PMID 37665633, 2023). "Our findings confirm the potential effects of TQ in inhibiting cell proliferation and inducing apoptosis of HL60 leukemia cells through indirectly targeting c-Myc oncogene expression by inhibiting JAK/STAT and PI3K/AKT/mTOR signaling." (PMID 35337104, 2022). "Using mouse E2A-PBX1+/preBCR+ leukemia cells, we tested several inhibitors targeting the PI3K/AKT/MTOR pathway." (PMID 35794338, 2022). "Tanshinone IIA, an abietane diterpenoid, isolated from Salvia miltiorrhizae, was reported to trigger autophagy in KBM-5 leukemia cells through AMPK activation and suppression of MTOR and RPS6KB/p70S6K." (PMID 36497321, 2022). "This compound initiates autophagy through the suppression of MTOR and RPS6KB/p70S6K of the JAK-STAT pathway in leukemia TF1 cells." (PMID 36497321, 2022). "Regarding signaling through a family of different Src kinases (including LYN and SRC), these are expressed in AML and their phosphorylation regulates leukemia cell proliferation and survival (including through LYN mediating mTOR activation)." (PMID 35053339, 2022). "STAT5, PI3K/Akt/mTOR and MEK/Erk pathways are activated by IL-7R-mediated signaling in healthy lymphocytes and leukemia cells." (PMID 35581375, 2022). "Using an in vivo model of leukemia, RPS6KA1 has been shown to promote the self-renewal of hematopoietic stem cells and disease progression through the regulation of the mTOR pathway." (PMID 34502231, 2021).
leukemia (continued). "As a negative modulator of autophagy, the hyperactivation of PI3K/Akt/mTOR axis leads to the inactivation of autophagy in AML cells and is vital for maintaining the oncogenic potential of leukemia stem cells." (PMID 34691211, 2021). "In our study, MPT0G449 exhibited strong anticancer activity in leukemia and showed an extensive inhibitory effect on both phosphorylated and total AKT/mTOR, STAT3/5, and MEK/ERK protein expression." (PMID 33986242, 2021). "STAT3 promotes the proliferation of leukemia cells through AKT/STAT3, Ras/Raf/MAPK and PI3K/AKT/mTOR, and other pathways." (PMID 33796529, 2021). "This leukemia is characterized by a single-copy deletion of the IKZF1 (IKAROS) tumor suppressor and increased activation of the PI3K/AKT/mTOR pathway." (PMID 33531656, 2021). "There are several signaling pathways that are known to be protagonists in the progression of leukemias, such as the PI3K/Akt/mTOR, Wnt/β-catenin, JAK/STAT, and NF-κB pathways." (PMID 32503270, 2020). "Hereafter, PI3K/AKT pathway inhibition is regarded as a therapeutic approach followed by the preclinical studies in leukemia cells in spite of the upregulated expression of P2RY14 in acute leukemia cells resistant to PI3K/mTOR inhibition." (PMID 32333246, 2020). "In another study, Tan IIA induced autophagic cell death viaactivation of AMPK and ERK and inhibition of mTOR and rapamycin(mTOR), ribosomal protein S6 kinase (p70 S6K) in KBM-5 leukemia cells." (PMID 32265690, 2020). "This relationship between NTS-induced mTOR downregulation and RNF126 upregulation was observed in several leukemia cell lines." (PMID 32131492, 2020). "Therefore, we investigated whether ROS could affect leukemia cell death or mTOR ubiquitination." (PMID 32131492, 2020). "The anti-leukemic effect of mTOR inhibition depends on the level of constitutive PI3K/Akt/mTOR pathway activation, leukemia-microenvironment crosstalk, and the release of mediators by both AML and stromal cells." (PMID 31319822, 2019). "Our previous study showed that Gnetin-C induces apoptosis in acute myeloid leukemia (AML) through simultaneously inhibiting the mTOR and MAPK pathways, which are essential for the survival of leukemia cells." (PMID 31234376, 2019). "DFX also exerts its anti-leukemia activity by inhibiting extracellular signal-regulated kinase (ERK) phosphorylation, repressing the mammalian target of rapamycin (mTOR) and NF-κB signaling pathway." (PMID 31519186, 2019). "Given the heterogeneity of leukemias, it is important to remark that there is variability within leukemias, in both in vitro and in vivo sensitivities to PI3K/Akt/mTOR inhibition." (PMID 30110936, 2018). "These miRNAs contribute to leukemia developments and progression by directly targeting the insulin-like growth factor 1 receptor (IGF1R) and mTOR." (PMID 30110936, 2018). "Several prior studies have highlighted abnormal activation of PI3K/AKT/mTOR and JAK/STAT pathways in childhood Ph-like ALL models and have demonstrated improved anti-leukemia efficacy upon combining type I JAK1/2 inhibitor ruxolitinib and PI3K/mTOR inhibitors." (PMID 29487712, 2018). "The control of the PI3K/Akt/mTOR axis by PTEN is fundamental for the self-renewal of HSCs and PTEN knock-out generates leukemia in mice." (PMID 30147674, 2018). "Conversely, PLK inhibitors and those targeting PIK3/mTOR and separately MEK and Chk1, are likely to have minimal neutropenic potential whilst having considerable activity against leukemias." (PMID 28938529, 2017). "Compounds targeting the PI3K/Akt/mTOR pathway had an effect on the viability of CP CML MNCs ex vivo, but the leukemia-specificity was modest." (PMID 28186983, 2017). "In terms of autophagy regulation, tanshinone IIA has been reported to induce autophagic cell death of leukemia via activation of AMPK/mTOR and ERK/mTOR, as well as p70 S6K signaling." (PMID 26999089, 2016).